ESR2 (estrogen receptor 2)
Diseases named in the same sentence as ESR2 in open-access papers (continued):
Sharing a sentence is not in itself a finding about the gene and the disease.
cancer (continued). "ESR2+ stromal cells from disease eutopic tissue and ectopic lesion tissues are predominately enriched in cancer-related pathways." (PMID 41000819, 2025). "It was shown in other cancers that the mutual interplay of ESR2 and miRNA plays a role in cancer through the modulation of extracellular matrix components, which is one of the epigenetic mediators." (PMID 40362695, 2025). "To better characterize ESR2’s role in various cancer types, we carried out Gene Set Enrichment Analysis (GSEA)." (PMID 39201394, 2024). "We distinguished cancer types with significant changes in ESR2 expression levels compared to corresponding healthy tissue and concluded that ESR2 influences patient survival." (PMID 39201394, 2024). "ACIN1 and SYNE2 showed a combined effect with ESR2 on either OS or DFS in 9 out of 17 cancer types, TNFRSF13C showed a combined effect with ESR2 in 8 cancer types, and MDM4 showed a combined effect with ESR2 in 7 cancer types." (PMID 39201394, 2024). "Several studies have reported that ESR2 is involved in the regulation of mitochondrial function, oxidative stress, and cellular energy metabolism in cancer." (PMID 39767718, 2024). "Next, an online Kaplan-Meier plot was used to assess the predictive value of the PTGS2/ESR2/EGFR/JUN/MMP2 genes’ signature expression level on OS in numerous human cancers." (PMID 39707884, 2024). "The evaluation of the ESR2 gene also showed that AOH at a dose of 10 μM affected the tested gene in both normal as well as cancer cell lines." (PMID 37298472, 2023). "On the other hand, much less is known about estrogen receptor beta (ERβ, encoded by ESR2) and its importance in cancer." (PMID 35304506, 2022). "Mutations in ESR1, ESR2, and PGR genes were the most frequent alterations in multiple cancer types, followed by amplifications and deep deletions." (PMID 34322374, 2021). "To identify mutation sites in the ESR1, ESR2, and PGR genes, we assessed 10,189 samples from multiple cancer types." (PMID 34322374, 2021). "In the validation cohort, patients were well balanced in terms of age, sex, cancer stage, and treatments, except for pathology, between high and low ESR2 expression groups." (PMID 33332474, 2020). "We then compared ESR1 and ESR2 mRNA expression levels difference in 23 cancer types with both tumors and adjacent normal tissues." (PMID 32536040, 2020). "In common with other members of the nuclear receptor family, the ESR1 and ESR2 genes are subject to alternative splicing with both C terminal and exon-skipping isoforms identified in cancer cell lines and human tissues including the testis." (PMID 31778358, 2020). "As an oncogenic factor, ESR1 promotes cell viability and division and plays a role in PCa inflammation; in contrast, ESR2 plays a protective role in PCa development because of its anti-cancer and pro-apoptotic properties." (PMID 30361641, 2018). "The gene encodes a transcription factor that responds to estrogen action and cancer, and will also form a heterodimer with ESR2." (PMID 23281828, 2012). "Notably, ERE was identified in the promoter of HES1 gene and both ESR1 and ESR2 were found to control HES1 expression in human cancer cells." (PMID 40506655, 2025). "Hence, we decided to look for genes that showed mRNA expression patterns similar to that of ESR2 in TCGA cancer types." (PMID 39201394, 2024). "To determine whether ESR2 expression level could be described as a potential biomarker in cancer, we searched the TISIDB database for correlations with the grade and stage of tumors." (PMID 39201394, 2024). "Interestingly, 20 out of 29 cancer types presented significant results (p-value < 0.05) when we analyzed ESR2’s influence on OS." (PMID 39201394, 2024).
cancer (continued). "We identified 12 potential genes associated with ESR2 expression in cancer tissue, previously not characterized in terms of ESR2." (PMID 39201394, 2024). "Further, assessment of somatic ESR2 mutations that emerge in response to cancer therapies have not been explored." (PMID 36926316, 2023). "Therefore, we used the cBioPortal web tool for further analysis of the genetic mutations in ESR1, ESR2, and PGR in multiple cancer types." (PMID 34322374, 2021). "To inquiry genetic alterations of ESR1, ESR2, and PGR that may be associated with tumorigenesis, we analyzed these in pan-cancer involving a total of 10,189 patients." (PMID 34322374, 2021). "It seems that ESR2 gene silencing plays a role in cancer progression." (PMID 33562134, 2021). "In addition, 112 ESR2 and 214 PGR nonsynonymous mutation sites were detected in different cancers, with the highest frequency mutations in R227H/C/L and R740Q/*." (PMID 34322374, 2021). "ESR1 and ESR2 expression have been investigated in many cancer types." (PMID 32536040, 2020). "Rs4986938 of ESR2 has been investigated in many types of cancer." (PMID 31523634, 2019). "In contrast to the findings for all-cause mortality however, current HT was found to greatly increase the risk of cancer-specific mortality for women homozygous TT or AA for ESR1 rs2234693 and rs9340799, respectively, and for those with the GG genotype of ESR2 rs1271572." (PMID 22457817, 2012). "Additionally, 12 cancer types yielded significant results with regard to ESR2’s influence on DFS." (PMID 39201394, 2024). "Thus, we hypothesized that ESR1 and ESR2 might involve in the progression and prognosis of various cancers." (PMID 32536040, 2020). "First, we compared the fold change in expression of the ER-related receptors ESR1, ESR2, ESRRA, ESRRB, ESRRG, and GPER1 in the four female cancers." (PMID 38582811, 2024). "The expression patterns of estrogen and its related proteins, including estrogen-related receptor alpha (ESRRA), ESRRG, ER-alpha (ESR1), and ER-beta (ESR2), were examined in the HPA in different types of cancers." (PMID 37240447, 2023). "In this study, we conducted a comprehensive pan-cancer analysis of ESR1, ESR2, and PGR on the basis of online databases." (PMID 34322374, 2021). "ESR1 Cr values strongly positively correlated with ESR2 Cr only in unchanged tissue and was moderately correlated with both PELP1 Cr and SRC Cr in cancer affected tissue." (PMID 34207568, 2021). "To explore the expression of ESR1, ESR2 and PGR in pan-cancer, we analyzed their mRNA levels via GEPIA2." (PMID 34322374, 2021). "To investigate the distribution of ESR1, ESR2, and PGR isoforms in pan-cancer, we compared their expression levels via GEPIA2." (PMID 34322374, 2021). "ESR1-201, ESR1-202, ESR2-004, ESR2-005 and PGR-001 were mostly commonly used transcribed isoforms in different cancer types." (PMID 34322374, 2021). "Through this comprehensive pan-cancer analysis, the feasibility of using ESR1, ESR2, and PGR as prognostic markers and therapeutic targets for multiple cancers was evaluated." (PMID 34322374, 2021). "To assess the relevance of ESR1, ESR2, and PGR with immune system that plays critical roles in cancer progression, we first compared their co-expression with the abundance of immunomodulators." (PMID 34322374, 2021). "To investigate the potential roles of ESR1, ESR2, and PGR in prognosis, we analyzed the correlation of their expression with pan-cancer survival." (PMID 34322374, 2021). "The pan-cancer mRNA expression levels, genetic variations, and prognostic values of ESR1, ESR2, and PGR were analyzed using the Gene Expression Profiling Interactive Analysis 2 (GEPIA2) and cBioPortal." (PMID 34322374, 2021). "Our results revealed genetic alterations in ESR1, ESR2, and PGR in multiple cancer types, including amplification, fusion, deep deletion, missense mutation, and truncating mutation." (PMID 34322374, 2021).
cancer (continued). "Generally, the results of this study indicated that ESR1, ESR2, and PGR can be regarded as predictive and prognostic biomarkers across different cancer types." (PMID 34322374, 2021). "Together, the potential roles of ESR1, ESR2 and PGR in cancer are likely in an immune system-dependent manner." (PMID 34322374, 2021). "Only in cancer affected tissue, ESR1/SRC and ESR2/PELP1 ratios were both positively correlated with PELP1/SRC (moderately strong) and ESR2/SRC (strong), respectively." (PMID 34207568, 2021). "There were also differences in the types and frequencies of genetic alterations in ESR1, ESR2, and PGR in multiple cancer types." (PMID 34322374, 2021). "For each cancer type, the expression of ESR1 and ESR2 across different patients’ clinical variables were analyzed." (PMID 32536040, 2020). "Estradiol is an agonist ligand of the Estrogen Receptors (ER, primarily ERα coded by the ESR1 gene, but also ERβ coded by the ESR2 gene, and the more elusive Estrogen-related Receptors ERRs), and promotes the proliferation of cancer cells." (PMID 31645610, 2019). "Immediate effects of siRNA on SK-BR-3 growth on the Test Cancer Biochip were observed at day 2 for ERBB2, ESR2, CSK, CTSL2, and BRAF siRNAs." (PMID 23049944, 2012). "ESR2 was not considered a sole prognostic factor in 9 cancer types in terms of OS and 17 cancer types in terms of DFS." (PMID 39201394, 2024). "To review if ESR2 may be considered a prognostic factor, we examined the influence of ESR2 mRNA expression level on overall survival (OS) and disease-free survival (DFS) across various cancer types within the TCGA database." (PMID 39201394, 2024). "Interestingly, the ESR1/ESR2 ratio was characterized by a strong, negative correlation with ESR2/PELP1 ratio in OCP, and moderately strong with ESR2/SRC ratio in both benign changes of ovary and cancer affected tissue." (PMID 34207568, 2021). "Together, ESR1, ESR2, and PGR are differentially expressed in multiple cancer types." (PMID 34322374, 2021). "ESR1, ESR2, and PGR are potential prognostic markers and therapeutic targets, as well as important factors for the prediction, evaluation, and individualized treatment in several cancer types." (PMID 34322374, 2021). "However, the roles of ESR1, ESR2, and PGR in other cancer types have rarely been studied and further investigations are needed to reach a consensus." (PMID 34322374, 2021). "Considering these results, we hypothesized that genetic alterations in ESR1, ESR2, and PGR play an essential role in cancer progression and combining the expression levels of ESR1, ESR2, and PGR provide prognostic value." (PMID 34322374, 2021). "Together, ESR1, ESR2, and PGR isoforms are differentially expressed in different cancer types." (PMID 34322374, 2021). "Accordingly, ESR1, ESR2, and PGR may be prognostic biomarkers as well as potential therapeutic targets for a variety of cancer types, necessitating further evaluation." (PMID 34322374, 2021). "Additionally, prognostic analysis suggested that ESR1, ESR2, and PGR were significantly correlated with OS and RFS in patients with specific cancer types." (PMID 34322374, 2021). "In our study, we selected ESR1, ESR2, and PGR for an in-depth analysis of mRNA expression, genetic alternations, and clinical outcomes as well as the co-expression of these genes with immunomodulatory factors in a variety of cancer types." (PMID 34322374, 2021). "ESR2 mRNA was undetectable in all our cancer cell lines and patient samples tested (data not shown)." (PMID 32132580, 2020). "In contrast, there was increased expression of ESR2 (ERβ) mRNA in OC samples from patients who had VI in comparison to cancer samples from patient who had no VI (p = 0.01)." (PMID 29390981, 2018). "For example, it could be that genes specific to common cancer-related pathways are those that are well studied, such as BCL2 or ESR2." (PMID 20459635, 2010).
cancer (continued). "Thus, it cannot be ruled out that such mechanisms (herein involving ESR2) are not unique for cancer cells, but are also operating in physiological conditions in SC." (PMID 40506655, 2025). "The results showed that the expression of 2682 LncRNAs in cancer and noncancerous tissues is significantly different, and 15 of them may be directly bound to the ERβ/ESR2 promoter (Table." (PMID 38641065, 2024). "To assess if downstream ERβ1 specific transcriptional programs were present in ESR2 + TNBC cancers we performed Pearson correlation analysis between the high ESR2 expressing group in TNBC and downstream genes known to be upregulated or downregulated following ESR2 activation." (PMID 37208678, 2023). "Hence, in the present study, we investigated the potential of ESR1, ESR2, and PGR as predictive and prognostic biomarkers in multiple cancer types from an immuno-oncological perspective based on bioinformatics analysis to provide a reference for future studies and the application of immunotherapies." (PMID 34322374, 2021). "Interestingly, even no significant differential ESR1 and ESR2 expression were found in many carcinomas." (PMID 32536040, 2020). "Interestingly, the opposite pattern was observed for the MET/ESR2 coexpression in which high coexpression was associated with younger age at diagnosis, increased NPI, advanced stage and grade of carcinoma, hormone receptor-negative status, and non-luminal tumors." (PMID 39742369, 2024). "Our study provides comprehensive evidence that ESR1, ESR2, and PGR are feasible prognostic markers and therapeutic targets for multiple cancers and that they could be a factor for disease prediction, disease evaluation, and individualized treatment in various types of cancer." (PMID 34322374, 2021). "OncoTree Code was selected to indicate the ratio of cancer patients with/without genetic alterations in ESR1, ESR2, and PGR, and results suggested the potentially critical roles of ESR1, ESR2 and PGR in onset of multiple cancers." (PMID 34322374, 2021). "ESR2/SRC ratio was positively, very strongly correlated with PELP1/SRC ratio in tissue lack of any changes and strong in cancer affected tissue." (PMID 34207568, 2021). "In case of ESR2 Cr, cancer affected tissue showed a significant negative correlation with ESR1/ESR2 ratio (moderately strong) and positive with both ESR2/PELP1 (very strong) and ESR2/SRC (moderately strong)." (PMID 34207568, 2021).
adenocarcinoma (26 papers, 2011 to 2025). A common cancer characterized by the presence of malignant glandular cells. "ESR2 expression is higher in normal lung, is associated with poor prognosis of NSCLC, and is elevated in male adenocarcinomas." (PMID 35924166, 2022).
cardiovascular diseases (16 papers, 2012 to 2025). "ESR2 mediates the protective effects of estrogens against cardiovascular diseases by reducing the expression of inflammatory cytokines and adhesion molecules, thus maintaining vascular homeostasis and preventing AS progression." (PMID 39596822, 2024). "Polymorphisms and haplotypes of the estrogen receptor-beta gene (ESR2) and cardiovascular disease in men and women." (PMID 34644788, 2021).
prostate (9 papers, 2010 to 2023). "ESR2 is regulated by AR and interacts with ESR1 to regulate prostate carcinogenesis through the modulation of genes involved in cell proliferation and apoptosis." (PMID 31523634, 2019).
metabolic disease (8 papers, 2008 to 2024). A congenital disorder (due to inherited enzyme abnormality) or acquired (due to failure of a metabolically important organ) disorder resulting from an abnormal metabolic process. "The ESR1 and ESR2, which are involved in the estrogen signaling pathway, are highly related to menopause-related metabolic diseases." (PMID 31752216, 2019). "An imbalance between ESR1 and ESR2 in the adipose tissue could therefore affect the development of metabolic diseases." (PMID 30217154, 2018).
neurological disorders (4 papers, 2019 to 2024). "Most BPA-perturbed proteins interact with hubs in the brain known to be involved in several neurological disorders, such as APP and ESR2." (PMID 37664457, 2023).
Respiratory disease (1 paper, 2013). "Respiratory disease biomarkers like ARG2, SCNN1G, EPB41L4B, CSF1, PTEN, TUBB1, and ESR2 were also detected." (PMID 24382964, 2013).
ESR2 also shares sentences with these, for which no sentence is quoted: non-small cell lung carcinoma (26 papers); osteosarcoma (23); colitis (19); infection (16); hepatocellular carcinoma (14); lymph node metastasis (12); seminoma (12); bladder tumors (10); pancreatic cancer (10); Parkinson disease (10); inflammatory bowel disease (9); invasive breast carcinoma (9); ovarian tumor (9); papillary thyroid carcinoma (9); Arthritis (7); astrocytomas (7); Hyperglycemia (7); malignant pleural mesothelioma (7); renal cell carcinoma (7); Stroke (7); cervical cancer (6); Hepatic steatosis (6); lentivirus infection (6); liver disease (6); medulloblastoma (6); neuroblastoma (6); neurodegenerative disease (6); anxiety disorder (5); brain disorder (5); Cerebral ischemia (5).
A further 320 diseases each share a sentence with ESR2 in 5 papers or fewer.